BDNF (brain derived neurotrophic factor)
Diseases named in the same sentence as BDNF in open-access papers (continued):
Sharing a sentence is not in itself a finding about the gene and the disease.
glaucoma (continued). "In an experimental model of glaucoma induced by elevated IOP, aged mice that engaged in voluntary exercise maintained brain-derived neurotrophic factor (BDNF) levels comparable to those of young sedentary mice and exhibited similar preservation of RGCs." (PMID 41228444, 2025). "Using these techniques, multiple studies have uncovered the potential role of NTs in protecting RGCs during direct neurodegeneration, with BDNF and NGF delivery promoting RGC survival in models of experimental glaucoma." (PMID 39944766, 2025). "In primary open-angle glaucoma (POAG) patients, significantly reduced brain-derived neurotrophic factor (BDNF) levels adversely affect RGC and trabecular meshwork cell survival, correlating with disease severity." (PMID 38725662, 2024). "Research has shown significantly reduced levels of BDNF in the serum and aqueous humor of patients with normal tension glaucoma (NTG) and primary open-angle glaucoma (POAG)." (PMID 39458902, 2024). "Neurotrophic factors such as nerve growth factor (NGF), BDNF, CNTF, FGF-2, glial cell-line-derived neurotrophic factor (GDNF), neurturin (NRTN), and neuritin are particularly relevant to glaucoma." (PMID 39458902, 2024). "Therefore, understanding the intricate interactions between BDNF, TrkB, Shp2, and caveolin proteins holds significant promise for the development of novel therapeutic strategies to halt or delay disease progression and ultimately improve the clinical management of glaucoma patients." (PMID 37962455, 2024). "BDNF-mediated, CNTF-mediated, NGF-mediated, and GDNF-mediated neuroprotection in glaucoma has great potential, but retinal delivery is challenging, and adverse effects must be addressed." (PMID 38132117, 2023). "For example, BMD, commonly prescribed in clinics to reduce the IOP, was found to improve the BDNF production and preserve RGCs when administered systematically to mouse and rat models of IOP-independent glaucoma." (PMID 35668928, 2022). "Both BDNF and NGF are known promoters of RGC survival upon glaucomatous injury and their application as potential neuroprotective drugs in glaucoma management is well-studied." (PMID 35681479, 2022). "In summary, our study showed that the expression levels of TNF-α, IL-2, IL-6, IL-8, BDNF, MMP-2, MCP-1, VEGF, IFN-γ, LT-α, bFGF, PDGF-AA, and TIMP-1 were different among the 3 types of glaucoma." (PMID 36254076, 2022). "The obstruction of BDNF delivery and accumulation of TrkB at the ONH plays a vital role in the pathogenesis of glaucoma." (PMID 35668928, 2022). "The reduction in the retrograde transport of neurotrophic factors such as BDNF in RGCs, by increasing IOP, has been suggested as a critical factor for the degeneration of these cells in glaucoma." (PMID 33669765, 2021). "In glaucoma, transport of BDNF is compromised after elevations in IOP, while levels of BDNF are reduced in serum and tears of glaucoma patients." (PMID 33269115, 2020). "In a glaucoma animal model induced by chronic IOP, intraocular injection of the brain-derived neurotrophic factor increased the number of ribbon synapses." (PMID 32977518, 2020). "Repeated injections of BDNF or another type of delivery system may prolong the effects of this neurotrophic factor and should be further investigated to determine its application as a neuroenhancement therapy in glaucoma due to its ability to strengthen the synapse in the inner retina." (PMID 31142572, 2019). "Several studies have shown that BDNF acts as a potent neuroprotectant for RGCs after optic nerve (ON) injury and after increased IOP which mimics the primary open-angle glaucoma (POAG)." (PMID 29896439, 2018). "The novel vector outperformed conventional AAV2 BDNF25,26,56 (which express solely BDNF) and AAV2 TrkB, increasing our interest in this vector design as a possible treatment for glaucoma in the future." (PMID 30258047, 2018).
glaucoma (continued). "After injection of the extract on the 14th day we noted a strong expression of BDNF in both INL and ONL and a weaker expression in GCL, even if animals were sacrificed on 35th day following glaucoma." (PMID 29109409, 2017). "In our experiment, BDNF was highly expressed in inner nuclear layer (INL) and ganglion cell layer (GCL) in the healthy eyes compared with the sections from glaucoma eyes, where weaker expression of this neurotrophin was observed (mainly in GCL layer)." (PMID 29109409, 2017). "Based on this finding, we intended to deliver BDNF to the RGCs from a natural extraretinal source, the SC, in order to induce RGC neuroprotection in murine glaucoma models." (PMID 26560713, 2015). "Neurotrophins: The brain-derived neurotrophic factor (BDNF) and ciliary derived neurotrophic factor (CNTF) have been found to be decreased in glaucoma." (PMID 22737394, 2012). "Emerging evidence also suggests that exercise may exert neuroprotective effects, including the upregulation of brain-derived neurotrophic factor (BDNF) and improved mitochondrial function, potentially guarding against retinal ganglion cell damage in glaucoma." (PMID 40364241, 2025). "Thus, neurotrophic supplementation therapies, such as nerve growth factor (NGF), brain-derived neurotrophic factor (BDNF), or ciliary neurotrophic factor (CNTF), have been studied for preventing the progression of glaucoma." (PMID 39408817, 2024). "Our results may serve as a rationality for the clinical application of BDNF and PDGF-AA in glaucoma treatment." (PMID 36254076, 2022). "It has been reported that the expression of two important neurological factors BDNF and NGF in glaucoma patients was significantly reduced compared to healthy individuals; such reductions can lead to poor cell function and impaired nervous growth and development." (PMID 34646884, 2021). "Moreover, BDNF, VEGF-A, and PlGF levels, were found significantly decreased in the ONH of DBA/2J mice with severe glaucoma, compared to control D2-Gpnmb+ mice." (PMID 34530842, 2021). "Although in our study neither the BDNF nor the TrkB protein concentrations in rats with glaucoma were changed in VCtx (not shown), further spatio-temporal studies are needed to construct a more complete image of the neurotrophic alterations within the system." (PMID 32872441, 2020). "The seriousness of the retinal injury can be assessed by the increase in BDNF that does not express in the early stages of glaucoma." (PMID 32666339, 2020). "Consistently, BDNF levels are reduced in the serum and tears of glaucoma patients, suggesting that deficits in this neurotrophin may participate in RGC death in glaucoma and that BDNF may be a biomarker for glaucoma." (PMID 32218163, 2020). "Neurotrophic factors have also been studied as potential neuroprotective factors in neurodegenerative diseases, with brain-derived neurotrophic factor (BDNF) and ciliary-derived neurotrophic factor (CNTF) both having been shown to protect axotomized RGC and RGC in animal models of glaucoma." (PMID 29853847, 2018). "Unfortunately, viral vector-induced overexpression of BDNF in the SC did not result in enhanced RGC survival in none of the two glaucoma models." (PMID 26560713, 2015). "After outlining the RGC degeneration profiles, the temporal patterns of BDNF and TrkB-FL/TrkB-T1 levels in the retina and superior colliculus (SC), the primary target for RGC axons in rodents, were visualized in both models of experimentally induced glaucoma." (PMID 26560713, 2015). "Although the previously reported temporary neuroprotective effect of intravitreally delivered recombinant BDNF was confirmed, viral vector-induced BDNF overexpression in the SC did not result in protection of the RGCs in the glaucoma models used." (PMID 26560713, 2015).
glaucoma (continued). "This is of potential significance since glaucoma is a disease of RGC degeneration in the elderly, which may be ameliorated by exogenous neurotrophic factors such as brain-derived neurotrophic factor (BDNF)." (PMID 19421410, 2009). "As BDNF is known to play an important role in neuronal survival, it has been shown that the administration of exogenous BDNF following optic nerve injury in rodents with induced glaucoma and in glaucoma patients slows RGC degeneration, glaucoma being characterized by RGCs and optic nerve atrophy." (PMID 40003672, 2025). "In addition, the role of neurotransmitters such as glutamate, glycine, dopamine, serotonin, etc., and neurotrophins, such as the brain-derived neurotrophic factor (BDNF), neurotrophin-3 (NT3), and neurotrophin-4/5 (NT4/5) in glaucoma, has also been extensively investigated." (PMID 37305138, 2023). "In animal models of glaucoma, disrupted BDNF axonal transport was observed, and BDNF injection into the superior colliculus (SC) of neonatal hamsters resulted in a 13–15-fold reduction in RGC pyknosis, showing that the BDNF plays a significant role in promoting the RGC survival." (PMID 35668928, 2022). "BDNF plays a role in a myriad of pathophysiologic pathways (TGF-β, MAP kinase, Rho kinase, JNK, PI-3/Akt, PTEN, Bcl-2, Caspase, Calcium-Calpain) and could serve as a promising candidate for devising therapies to enhance RGC survival in glaucoma." (PMID 35668928, 2022). "The BDNF levels in L and R retinas were strongly correlated, which suggests that dysfunction of the glaucomatous eye is not isolated, and draws the line of changes in the contralateral eye in which no glaucoma was induced." (PMID 32872441, 2020). "Viral vector-induced BDNF overexpression in the superior colliculus, thought to boost the retrograde neurotrophin delivery, did not increase BDNF in the retina and failed to protect RGCs in the glaucoma models used." (PMID 32872441, 2020). "The results of the present study demonstrated a potential negative effect BDNF Val66Met polymorphism has on ON damage in NMOSD, which contrasts with the previous glaucoma study where the Met alleles exhibited protective effects on OAG progression in a gender-specific way." (PMID 31803011, 2019). "Its role in glaucoma has not been studied in depth, and since BDNF is critical to ganglion cell survival, there is the potential that the SNP may be a factor in certain subtypes of glaucoma." (PMID 29896439, 2018). "It is important to note that BDNF levels in the serum and tears of glaucoma patients are significantly lower than in control subjects, suggesting that deficits in this neurotrophin may participate in RGC death in glaucoma." (PMID 30524222, 2018). "In a rat model of experimental glaucoma, artificial elevation of IOP cripples the optic nerve head at the level of the lamina cribrosa, swelling nerve fibers and blocking the axonal flow of BDNF, while expression of the cognate receptor TrkB is increased at the optic nerve head." (PMID 30723498, 2017). "Recent evidence reported the interruption of BDNF retrograde transport and accumulation of TrkB at the optic nerve head in acute and chronic glaucoma models suggesting a role for BDNF retrograde signaling in RGC degeneration in glaucoma and RGC normal function." (PMID 25536045, 2014). "Although we did not count the number of cells in this study, we have previously demonstrated that after experimental glaucoma, RGCs die by apoptosis and that all RGCs are positive to BDNF, thus we cannot disregard the observation that the elevation of IOP reduced the number of BDNF positive cells." (PMID 20019879, 2009). "The levels of LT-α, BDNF, and PDGF-AA in the AH of different types of glaucoma have not been previously reported." (PMID 36254076, 2022). "Retrograde transport of BDNF and TrkB (but not TrkA) are affected following acutely increased IOP in rats, similar to a chronic model of glaucoma in non-human primates." (PMID 38983517, 2022).
glaucoma (continued). "The intravitreal injections of BDNF and PBS did not result in differences in IOP in either the sham or glaucoma surgery groups." (PMID 31142572, 2019). "As microglial activation may have been downregulated thanks to the saffron treatment, the glaucoma-related massive RGC death might not have occurred, thus making BDNF release unnecessary." (PMID 34768320, 2021).
ischemia (121 papers, 2004 to 2025). A hypoperfusion of the BLOOD through an organ or tissue caused by a PATHOLOGIC CONSTRICTION or obstruction of its BLOOD VESSELS, or an absence of BLOOD CIRCULATION. "Infarct volume, sensorimotor function, neurological deficits, and cellular expressions of brain-derived neurotrophic factor (BDNF), B-cell lymphoma 2 (Bcl-2), Bcl-2-associated X protein (Bax), and caspase 3 were evaluated 48 h after the induction of ischemia." (PMID 36750711, 2023). "BDNF and proBDNF and their associated proteins participated in the pathogenesis and recovered from photothrombotic ischemia." (PMID 35370607, 2022). "Multiple studies have shown that BDNF improves locomotor ability in rodents following experimental ischemia-induced neuronal loss." (PMID 22363780, 2012). "A further investigation was conducted into the levels pertaining to CREB and BDNF, which could alleviate the damage caused by ischemia (According to the results, the expression of BDNF was suppressed significantly after I/R surgery (p < 0.01)." (PMID 35095491, 2021). "Interestingly, neural progenitor cells can synthesize and secrete trophic factors such as BDNF, which has been implicated as a major mediator of endogenous ischemia-induced neurogenesis." (PMID 28230741, 2017). "Additionally, SGLT2 inhibitors have a variety of pleiotropic effects, such as preventing brain damage from ischemia/reperfusion, modifying pathways linked to the circadian rhythm, and raising levels of brain-derived neurotrophic factor (BDNF), which is essential for neuronal survival and plasticity." (PMID 40807290, 2025). "Our results are in line with the previous research, demonstrating that pre- and post-treatment with Escitalopram increased the BDNF level in the gerbil hippocampus after ischemia." (PMID 41302150, 2025). "In adult rats, global ischemia produced by either bilateral carotid artery occlusion or cardiac arrest (i.e., with total body ischemia) resulted in higher BDNF expression in the hippocampus compared to sham or controls in the 24 h after injury." (PMID 38397427, 2024). "The inter‐group comparison of the adhesive removal test times demonstrated that it was significantly lower in the Control and Sham CI groups when compared to the ischemia and BDNF treatment groups between the 1st and 7th days (p < 0.05)." (PMID 38520223, 2024). "Recently published studies presented the crucial role of brain-derived neurotrophic factor (BDNF) in ischemia." (PMID 38817358, 2024). "The inter‐group comparison of the rotarod test times demonstrated that they were significantly higher in the control and Sham CI groups when compared to ischemia and BDNF groups between the 1st and 7th days (p < 0.05)." (PMID 38520223, 2024). "The comparison of the groups based on the post‐CI infarct area demonstrated that it was significantly larger in the ischemia (34.7%) and BDNF (21.3%) groups when compared to the Control and Sham CI groups (p < 0.05)." (PMID 38520223, 2024). "In a rat ischemia–reperfusion injury model, EA reversed the reduction of BDNF induced by ischemia–reperfusion injury and enhanced the BDNF/TrkB pathway to promote neuroprotection." (PMID 37780709, 2023). "PI3K is able to be induced by neurotrophic factors (nerve growth factor, brain-derived neurotrophic factor, glial cell line-derived neurotrophic factor, and neurotransmitters, for instance), and the phosphorylation of Akt is also enhanced after ischemia." (PMID 36726841, 2023). "Although in this case the underlying regulatory mechanism was not investigated, it is possible that the BDNF‐CREB axis is involved since BDNF plays a vital neuroprotective role in ischemia." (PMID 37334527, 2023). "For instance, AAV-mediated delivery of BDNF to the striatum 4–5 weeks before modeling ischemia reduced the death of rat brain neurons in a transient model of middle cerebral artery occlusion." (PMID 36077134, 2022).